IFIH1 (interferon induced with helicase C domain 1)
Diseases named in the same sentence as IFIH1 in open-access papers (continued):
Sharing a sentence is not in itself a finding about the gene and the disease.
systemic lupus erythematosus (67 papers, 2011 to 2025). An autoimmune multi-organ disease typically associated with vasculopathy and autoantibody production. "A mouse model of a gain-of-function MDA5 mutation (Ifih1 p.Gly821Ser) was generated through mutagenesis and displayed features of lupus." (PMID 34258050, 2021). "These polymorphisms in IFIH1 encoding MDA5 have been linked to several diseases, such as psoriasis, systemic lupus erythematosus, and type 1 diabetes." (PMID 34439917, 2021). "This is different from Ifih1 mutants, which develop an antibody-mediated lupus-like nephritis, or from Trex1-deficient mice, which develop lupus-like inflammation in multiple organs." (PMID 34764281, 2021). "Loss of function mutations in TREX1 and gain-of-function mutations of IFIH1 are both known to cause lupus-like phenotypes in humans and animal models, while both are involved in the pathways that activate IRF3." (PMID 32719713, 2020). "A missense mutation (G821S) of Ifih1 (encoding MDA5) results in a constitutively active form of MDA5 that causes mice to develop lupus-like symptoms including glomerulonephritis and a skin rash." (PMID 31681326, 2019). "We sought to determine if pro-inflammatory mediators previously shown to be associated with Mda5, resulting in a lupus-like phenotype in mice, also associated with IFIH1 in humans." (PMID 28234905, 2017). "Association between each of 135 genotyped SNPs in IFIH1 and four lupus-associated plasma mediators, IL-6, TNF-α, IFN-β, and IP-10, were investigated via linear regression." (PMID 28234905, 2017). "IFIH1 in particular is already known to harbour both a common SIgAD-associated variant and, at least in the case of one patient, a de novo gain-of-function missense mutation leading to systemic lupus erythematosus and IgA deficiency." (PMID 39241920, 2024). "Variants in IFIH1 (MDA5) have been implicated in Mendelian type I interferon-associated disorders, and single-nucleotide polymorphisms (SNPs) have been associated with more common inflammatory conditions such as systemic lupus erythematosus (SLE)." (PMID 34258050, 2021). "Additionally, mice with the IFIH1 G821S missense mutation exhibited lupus-like symptoms." (PMID 41327692, 2025). "Multiple studies indicated a pleiotropic effect of IFIH1 in modulating autoimmunity, and the IFIH1 gene region has been implicated in susceptibility to celiac disease (CD), systemic lupus erythematosus (SLE) and type 1 diabetes (T1D)." (PMID 34976003, 2021). "Heterozygous gain-of-function mutations of IFIH1 cause autosomal dominant autoimmune disorders, namely systemic lupus erythematosus (SLE) in mice, and SLE, Aicardi-Goutieres syndrome (AGS) or Singleton-Merten syndrome (SMS) in humans." (PMID 29018476, 2017). "Antiviral defenses are inappropriately activated in systemic lupus erythematosus (SLE) and association between SLE and the antiviral helicase gene, IFIH1, is well established." (PMID 28234905, 2017). "This balance is disrupted by gain-of-function IFIH1 mutations or loss of ADAR activity, triggering spontaneous IFN production in immune disorders, including Aicardi-Goutières syndrome (AGS) and systemic lupus erythematosus (SLE)." (PMID 40773553, 2025). "In this work, we focused on the human mutation of IFIH1 p.Arg779His, a mutation that causes AGS and monogenic lupus and it has also been found to cause systemic type I IFN upregulation in a mouse model." (PMID 38077314, 2023). "Patients with systemic lupus erythematosus of the Chinese genotype circulators of rs 1990760 IFIH1 had higher anti-dsDNA-positive results than the circulators of the CC and TT genotypes." (PMID 35327350, 2022). "Some single gene variants (SAMHD1, RNASEH2ABC, ADAR1, IFIH1, ISG15, ACP5, TMEM173) can cause monogenic lupus." (PMID 35783307, 2022). "Mutation in IFIH1 gene (cytosolic sensor of dsRNA) triggered chronic type I IFN production and aggressive disease in lupus-susceptible, Fcγ receptor-deficient mice." (PMID 24839407, 2014).
systemic lupus erythematosus (continued). "In addition to the detection of viral RNA, IFIH1 has been demonstrated to be involved in some inflammatory diseases, such as periodontitis and systemic lupus erythematosus." (PMID 33519803, 2020). "In this study, we employed Mendelian randomization to investigate the potential causal relationship between five genes, namely, DDX58, IFIH1, IRF7, STAT1, and ISG15, and systemic lupus erythematosus (SLE)." (PMID 39445158, 2024). "For instance, mutations in IFIH1, TREX1, or ADAR1 can cause diseases such as systemic lupus erythematosus (SLE), Aicardi-Goutières syndrome (AGS), and multiple sclerosis (MS)." (PMID 37396372, 2023). "In 2010 an association was found between SIgAD and an amino acid variant of the IFIH1 gene, associated with diabetes mellitus 1 (DM1) and systemic lupus erythematosus (SLE), supporting the hypothesis that autoimmune mechanisms may contribute to the pathogenesis of SIgAD." (PMID 35056437, 2022). "Our previous studies showed that increased copy number of the Ifih1 gene in mice elevated systemic IFN expression, which was insufficient to induce autoimmune symptoms by itself, but accelerated disease when combined with the lupus prone background of the FcγRIIB deficiency." (PMID 31681326, 2019). "Single nucleotide polymorphisms (SNPs) in IFIH1/MDA5 have been linked to autoimmune disorders, type 1 diabetes (T1D), psoriasis, rheumatoid arthritis, vitiligo, multiple sclerosis (MS), and Systemic Lupus Erythematosus (SLE)." (PMID 33498715, 2021). "Importantly, IFIH1, which controls anti-viral responses, will be a molecular target of diagnosis and treatment for systemic lupus erythematosus (SLE)." (PMID 25729389, 2015). "For instance, mice expressing multiple copies of an Ifih1 transgene spontaneously generate type I IFN and exhibit no overt phenotype, but increase disease severity when crossed with a lupus-prone strain." (PMID 29723194, 2018).
melanoma (64 papers, 2010 to 2026). A malignant, usually aggressive tumor composed of atypical, neoplastic melanocytes. "Interferon gene induced by helicase C domain 1 (IFIH1), also known as melanoma differentiation-associated 5 (MDA-5)." (PMID 38926794, 2024). "The IFIH1 gene, better known as melanoma differentiation-associated gene 5, is located at 2q24.3, and it encodes a cytoplasmic dsRNA helicase belonging to the RLR family." (PMID 35757684, 2022). "Recently, using preliminary results from large-scale association analyses of nonsynonymous SNPs, a novel locus for T1D was identified; IFIH1, which is also known as the melanoma a differentiation-associated 5 (MDA-5), or Helicard, gene." (PMID 22242199, 2012). "Melanoma differentiation–associated gene 5 (MDA5 or Helicard or IFIH1) recognizes long dsRNA." (PMID 34882751, 2021). "We also found that the overexpression of GBP4, DOK1, DDX60, and IFIH1 is correlated with better overall survival in several melanoma datasets." (PMID 34769455, 2021). "More specifically, the ablation of this demethylase in B16 melanoma triggers ERV transcription, which is sensed by the PRRs TLR3 and MDA5 (the latter being enconced by the Ifih1 gene), consequently eliciting type-I IFNs." (PMID 35681511, 2022). "Representative genes from this gene set such as Rsad2, Ifih1, Isg15, Ifit1 and Tmem173 were consistently found to be upregulated in all available NRF2 knockout melanomas." (PMID 32978520, 2020). "To assess the relevance of the innate immune response genes for human melanomas, we used RNA expression data from the TCGA SKCM metastatic melanoma dataset and analyzed the cumulative patient survival in relation to RSAD2 and IFIH1 expression." (PMID 32978520, 2020). "Both melanoma cell lines showed again a very comparable expression pattern of antiviral genes, with low expression of most genes, except for STING1, IFNAR1, IFNAR2, and IFIH1, which were moderately expressed." (PMID 40955425, 2025). "By analyzing the TCGA genomics, we also found that the gene alteration rates in the melanoma TCGA dataset were 12% for DDX60, 5% for CSNK1E, 2.8% for FGD1, 2.1% for GBP4, 4% for IFIH1, 1% for DOK1, and 0.7% for IRX3, and these alterations were not significantly correlated with mRNA expression." (PMID 34769455, 2021). "Finally, ADAR1i-124, like siAdar1, upregulated expression of IFN-stimulated genes (ISGs) such as Ifih1 (MDA5), Cxcl9, and Cxcl10 in Yumm1.7 melanoma and HGS2 ovarian cancer (OC) cells, indicating that ADAR1i-124 activates IFN signaling, a crucial step for effective ICB." (PMID 41608661, 2026). "For instance, RNA-seq analysis of human melanoma COLO829 cells transfected with MITF short hairpin RNA (shRNA) demonstrates an up-regulation of over 17 of the same 55 innate immune DEGs identified in Mitfmi-vga9/+ McSCs, including Ifih1, Ifit3, Irf7, Parp9, and Stat1 (GSE50686)." (PMID 29723194, 2018). "Furthermore, genes corresponding to the innate immune response such as RSAD2 and IFIH1 were strongly elevated in absence of NRF2 and coincided with immune evasion parameters in human melanoma datasets." (PMID 32978520, 2020).
Autoimmunity (58 papers, 2009 to 2025). The occurrence of an immune reaction against the organism's own cells or tissues. "It was shown that autoimmunity-protective IFIH1 missense variants decrease function of IFIH1, thus reducing the ability to bind DAMPs involved in autoimmune triggering with eventual decreased stimulation of innate immune responses." (PMID 30761886, 2019). "These authors concluded that the production of type I interferons driven by the IFIH1 could be under positive selection within human populations by protecting against viral challenge but at the cost of promoting the risk of autoimmunity." (PMID 37834254, 2023). "Single nucleotide polymorphisms (SNPs) in DDX58 (encoding RIG-I) and IFIH1 (encoding MDA5) were found in patients with autoimmune and autoinflammatory diseases, such as SLE, Aicardi-Goutières syndrome (AGS), T1D, psoriasis, and Singleton-Merten syndrome (SMS)." (PMID 35734577, 2022). "Of all the SNPs we studied, only IFIH1/2q24 (rs2111485 in LD with rs1990760) has been associated with both T1D risk and progression to T1D, whereas, the others have been linked to other autoimmune conditions." (PMID 36181724, 2022). "Alternatively, variants found at genes under balancing selection could be conferring susceptibility to different pathogens and their effect on autoimmunity would be a consequence of past humans adaptations, as suggested recently for IFIH1, a innate immunity gene involved in resistance to virus." (PMID 21745391, 2011). "IFIH1 is reported to be associated with MDA5-mediated chronic type I IFN gene signature and accelerated autoimmunity." (PMID 38912505, 2024). "Adjusting for non-genetic covariates, GADA loss was associated with low-risk HLA class II genotypes (P = 0.005), and SNPs associated with autoimmunity RELA/11q13 (P = 0.017), LPP/3q28 (P = 0.004), and negatively with IFIH1/2q24 (P = 0.018)." (PMID 36181724, 2022). "The delicate balance between the recognition of self- versus foreign RNA is well illustrated by the IFIH1 A946T allele, which encodes a variant of MDA5 that enhances anti-viral immunity, but increases the risk of autoimmunity." (PMID 33281822, 2020). "The delicate balance between the recognition of self- vs. foreign RNA is well illustrated by the IFIH1-A947T allele, which encodes a variant of MDA5 that enhances anti-viral immunity, but increases the risk of autoimmunity." (PMID 31139185, 2019). "The findings indicated that IFIH1 genotypes impacted progression from autoimmunity to diabetes development, which is consistent with the notion that protective genotypes downregulate responses to environmental insults even after the initiation of autoimmunity." (PMID 28829396, 2017). "Our finding of a significantly increased prevalence of EV-RNA in children positive for mAAb, regardless of their IFIH1 genotype, suggests that a dysregulated immune response and ongoing autoimmunity may interfere with the control and/or clearance of EV infection." (PMID 35867130, 2022).
type 1 diabetes (58 papers, 2007 to 2025). "Type 1 diabetes susceptibility genes have previously been found to interact with Caesarean section (IFIH1) or to be associated with increased progression to stage 3 type 1 diabetes (TNFAIP3, CTSH, MIR2681HG)." (PMID 38819466, 2024). "In conjunction, we found polymorphisms in OAS, MX1 and IFIH1 that indicate predisposition to type 1 diabetes." (PMID 33973017, 2021). "Single nucleotide polymorphisms in the IFIH1 results in fatal genetic disorders such as Aicardi–Goutières syndrome and Singleton–Merten syndrome, and in increased risk of type I diabetes in humans." (PMID 34439917, 2021). "The SNP rs2111485 was located 14 kb downstream of IFIH1 and was the SNP with the strongest eQTL signal associated with type 1 diabetes out of 90 SNPs found in this gene." (PMID 33973017, 2021). "Transcript analyses in human islets indicate that expression of several genes connected to antiviral response increases including IFIH1 (well established type 1 diabetes risk gene) and RSAD2 in virus infected islet cells." (PMID 33154504, 2020). "Carriers of pLOF variants in IFIH1 were protected against type 1 diabetes, psoriasis, and vitiligo in UK Biobank." (PMID 29691411, 2018). "It has been shown that rare variant or reduced expression of IFIH1 protects against type 1 diabetes." (PMID 28427244, 2017). "In contrast, certain supposed LoF SNPs in IFIH1, including the nonsense variant p.Glu627∗ (rs35744605), confer protection against type 1 diabetes." (PMID 29018476, 2017). "IFIH1 also identified as a type 1 diabetes (T1D) susceptible loci and a cause gene by re-sequencing the genomic regions initially identified by GWAS." (PMID 23997649, 2013). "A more recent example is provided by a study which identified four rare variants acting independently on type 1 diabetes (T1D) risk through targeted resequencing of IFIH1, a gene located in a region previously associated with T1D by GWAS." (PMID 23922232, 2013). "For example, the identified rare variants in BRCA1 and BRCA2 gene all increase risk of breast cancer, and the four rare variants identified in IFIH1 gene all protect against type I diabetes." (PMID 23472070, 2013). "The rs1990760 polymorphism of interferon induced with helicase C domain 1 (IFIH1) has been associated with type 1 diabetes mellitus (T1DM)." (PMID 24386202, 2013). "Clinical and laboratory characteristics of patients with type 1 diabetes mellitus, broken down by the different genotypes of the IFIH1 rs1990760 (G/A) polymorphism." (PMID 24386202, 2013). "Polymorphisms in the IFIH1 (common rs1990760 and four rare rs35667974, rs35337543, rs35744605, rs35732034) have been convincingly associated with type 1 diabetes." (PMID 23144876, 2012). "Because Coxsackie and other enteroviral infections are epidemiologically linked to type 1 diabetes (T1D) incidence, it was suggested that IFIH1 polymorphism acts as a molecular link between the specific viral trigger and the autoimmune response in T1D." (PMID 22242199, 2012). "Genetic variants of IFIH1, one common and four rare SNPs have been associated with lower risk for type 1 diabetes." (PMID 22110759, 2011). "IFIH1 is causal in type 1 diabetes based on the protective associations of four rare variants, where the derived alleles are predicted to reduce gene expression or function." (PMID 20844740, 2010). "An RNA helicase named IFIH1 is also involved in the innate immune response to viral infection as a risk factor for type 1 diabetes." (PMID 20142874, 2009). "A genome-wide association study of nonsynonymous SNPs identified a type 1 diabetes locus in the IFIH1 (also known as mda-5 or Helicard) present on chromosome 2q24.3region." (PMID 20142874, 2009). "Recent studies showed that a genetic variation within the interferon induced helicase domain 1 (IFIH1) locus (rs1990760 polymorphism) is an additional risk factor in type 1 diabetes and Graves' disease (GD)." (PMID 19961590, 2009).
type 1 diabetes (continued). "Recently, a novel locus called Interferon-induced helicard (IFIH1), rs1990760, was identified to be associated with type 1 diabetes (T1D) and Graves' disease." (PMID 19961590, 2009). "The aim of the present study was to investigate the role of the interferon induced with helicase domain 1 (IFIH1) A946T (rs1990760 A>G) variant in rheumatoid arthritis (RA), as this was recently associated with susceptibility to type 1 diabetes." (PMID 17442111, 2007). "In addition to AGS IFIH1, SNP risk alleles have also been identified in a range of autoinflammatory and autoimmune conditions such as type 1 diabetes, vitiligo, psoriasis, arthritis, multiple sclerosis, and SLE (74, 96, 142, –, 145)." (PMID 40552831, 2025). "In addition to Mendelian disorders, IFIH1 SNPs have been associated with type 1 diabetes (T1D), Graves' disease, and SLE, all of which can affect ocular health." (PMID 34258050, 2021). "Several SNPs in IFIH1, which could be linked to risk of and protection against type 1 diabetes, have previously been identified and may modify the structure and function of IFIH1." (PMID 33973017, 2021). "This strategy was used to detect rare variants in IFIH1 conferring protection to type I diabetes." (PMID 23472070, 2013). "In addition, a human genome-wide SNP scan identified the viral RNA receptor gene region IFIH1 (interferon induced with helicase C domain 1) as a type 1 diabetes susceptibility gene." (PMID 24147110, 2013). "This hypothesis was greatly sparked when a genome-wide association study of type 1 diabetes identified a significant relation with a common polymorphism in IFIH1." (PMID 22110759, 2011). "The primary aim of the present study was to assess in healthy children whether the IFIH1 polymorphisms associated with type 1 diabetes can predict frequency, viral load, or duration of gut infections with enterovirus." (PMID 22110759, 2011). "The IFIH1 alleles that had been previously associated with reduced type 1 diabetes risk were predicted to be loss of function variants, and may thus confer increased risk for enterovirus infection." (PMID 22110759, 2011). "The mechanisms relating IFIH1 polymorphisms to type 1 diabetes, and if enterovirus is involved here, remains unclear and paradoxical." (PMID 22110759, 2011). "Future analysis of the level of expression of VP1 within islet cells and/or the frequency of VP1-positive cells within pancreatic islets may provide further insights into the effects of genetic predisposition to type 1 diabetes by the common variant in IFIH1 (rs1990760, Thr946Ala)." (PMID 35867130, 2022). "Our aim was to test whether these type 1 diabetes-associated IFIH1 polymorphisms are associated with the occurrence of enterovirus infection in the gut of healthy children, or influence the lack of association between gut enterovirus infection and islet autoimmunity." (PMID 22110759, 2011). "If so, this would influence the observed association between enterovirus frequency and type 1 diabetes in the population, and failure to account for IFIH1 SNPs in population studies could be hypothesized to “conceal” relations between enterovirus and islet autoimmunity or type 1 diabetes." (PMID 22110759, 2011). "The SNP rs3788964 was located 35 kb upstream of the transcription start site in IFIH1, rs13422767 was located 24 kb downstream, and rs77088072 (a novel SNP in relation to type 1 diabetes) and rs3747517 were located inside the IFIH1 gene." (PMID 33973017, 2021). "The T1DGC 6K SNP scan and follow-up studies confirmed that type 1 diabetes associations at INS,IFIH1 (interferon-induced helicase), and KIAA0350 and identified an additional disease association on chromosome 21q22.3 in the UBASH3A locus." (PMID 20142874, 2009).